RHOBTB3 (Rho related BTB domain containing 3)
Description:
Rab9-regulated ATPase required for endosome to Golgi transport. Involved in transport vesicle docking at the Golgi complex, possibly by participating in release M6PRBP1/TIP47 from vesicles to permit their efficient docking and fusion at the Golgi. Specifically binds Rab9, but not other Rab proteins. Has low intrinsic ATPase activity due to autoinhibition, which is relieved by Rab9.
Synonyms: KIAA0878
Tractability: PROTAC: ubiquitination databases record sites on it.
Gene: Protein-coding gene on chromosome 5 (95,713,522 to 95,824,383, forward strand). Ensembl gene ENSG00000164292.
Subcellular location: Golgi apparatus
Subcellular location (Human Protein Atlas): Vesicles
Pathways (Reactome):
Signal Transduction: RHOBTB3 ATPase cycle
Vesicle-mediated transport: Retrograde transport at the Trans-Golgi-Network
Gene Ontology:
Molecular function: ATP binding; ATP hydrolysis activity; protein binding; small GTPase binding; ubiquitin protein ligase binding; GTPase activity
Biological process: retrograde transport, endosome to Golgi; proteasome-mediated ubiquitin-dependent protein catabolic process; regulation of proteolysis
Cellular component: extracellular exosome; Golgi apparatus; cytoplasm; trans-Golgi network membrane; cytosol
Genetic constraint (gnomAD): Loss-of-function variants: 19 observed, 36.17 expected, observed/expected ratio (o/e) 0.53, 90% interval 0.37 to 0.77. The upper end of that interval is the gene's LOEUF score, 0.77, which puts it in group 3 of 6, group 1 being the genes least tolerant of losing a copy. Missense variants: 378 observed, 481.49 expected, observed/expected ratio (o/e) 0.79, 90% interval 0.72 to 0.86. Synonymous variants: 166 observed, 186.14 expected, observed/expected ratio (o/e) 0.89, 90% interval 0.79 to 1.01.
Homologues: Orthologues: chimpanzee RHOBTB3 (99% identical), macaque RHOBTB3 (99% identical), pig RHOBTB3 (97% identical), dog RHOBTB3 (97% identical), rat Rhobtb3 (96% identical), mouse Rhobtb3 (96% identical), rabbit RHOBTB3 (94% identical), guinea pig RHOBTB3 (93% identical). Paralogues in human: RAC1 (13% identical), RAC3 (12% identical), RHOU (12% identical), RAC2 (11% identical), RHOA (11% identical), RHOG (11% identical), RHOQ (11% identical), CDC42 (11% identical), RHOB (10% identical), RHOC (10% identical), RHOT1 (10% identical), RHOBTB2 (10% identical), and 10 more.
Diseases named in the same sentence as RHOBTB3 in open-access papers:
RHOBTB3 is named in the same sentence as 26 diseases in open-access papers, as found by Europe PMC text mining. Sharing a sentence is not in itself a finding about the gene and the disease. The quoted sentences say what the papers report.
breast carcinoma (4 papers, 2010 to 2025). "RHOBTB3 gene is a gene encoding a member of the Rho GTPase family, and it has been pointed out that the expression level of RHOBTB3 is significantly increased in breast cancer tissues." (PMID 40909283, 2025). "The RHOBTB3 gene, harbouring SNP rs3777218, was identified as a putative breast cancer anti-estrogen resistance gene." (PMID 21062454, 2010). "RhoBTB3’s part in breast cancer deterrence is even less understood." (PMID 37762375, 2023). "Downregulation of RHOBTB2 and RHOBTB3 is common in breast cancer." (PMID 29423119, 2018).
renal carcinoma (2 papers, 2021 to 2023). A carcinoma arising from the epithelium of the renal parenchyma or the renal pelvis. "Similar to our findings, human renal carcinomas express a low level of RhoBTB3, and RhoBTB3 deficiency can significantly enhance the Warburg effect as well as accelerate xenograft growth." (PMID 34093823, 2021). "Furthermore, a negative correlation was established between miR-142-3p and RhoBTB3 in KIRC (P < 0.05), suggesting that miR-142-3p and RhoBTB3 play an inverse function in renal cancer cells." (PMID 37045834, 2023).
Type 2 Diabetes (2 papers, 2023 to 2024). "Last, RHOBTB3 plays a central role in transporting secretory proteins from endosomes to the Golgi apparatus and has been associated with type 2 diabetes in primary human islets as well as palmitic acid exposure in EndoC-βH1 cells." (PMID 38967666, 2024).
Alzheimer disease (1 paper, 2016). A progressive, neurodegenerative disease characterized by loss of function and death of nerve cells in several areas of the brain leading to loss of cognitive function such as memory and language. "Large scale transcriptional studies suggest that RhoBTB3 might be implicated in the development of psychotic disorders and Alzheimer’s disease." (PMID 27314390, 2016). "RHOBTB3 has also been proposed as a candidate vulnerability gene for Alzheimer’s disease, vulnerability being defined as higher expression in the CA1 versus CA3 region of the hippocampus and increased expression in disease." (PMID 27314390, 2016).
colorectal cancer (1 paper, 2021). A primary or metastatic malignant neoplasm that affects the colon or rectum. "Circ-RHOBTB3 expression is reduced in colorectal cancer tissues, and lower circ-RHOBTB3 levels are significantly associated with advanced clinical stage and greater risk of metastasis." (PMID 34881248, 2021).
glioma (1 paper, 2015). A benign or malignant brain and spinal cord tumor that arises from glial cells (astrocytes, oligodendrocytes, ependymal cells). "Seven Rho GTPases (RND1, RND3, RAC3, RHOA, RAC2, RAC1 and RHOC) showed a significantly greater connectivity in grade IV glioma and seven (CHP, RHOD, RHOF, RHOB, RHOQ, RND2, RHOBTB3) showed greater connectivity in grade II glioma." (PMID 26132659, 2015).
leukemia (1 paper, 2021). A malignant (clonal) hematologic disorder, involving hematopoietic stem cells and characterized by the presence of primitive or atypical myeloid or lymphoid cells in the bone marrow and the blood. "Consistently, three datasets indicated increased RHOBTB2 expression; six datasets and five datasets showed reduced RHOBTB1 and RHOBTB3 expression, respectively, in leukemia compared to normal samples in the ONCOMINE database." (PMID 34074803, 2021). "Therefore, the results above suggest that both RHOBTB2 and RHOBTB3 may be potential prognostic factors for patients with leukemia, and RHOBTB2 showed better prognostic performance." (PMID 34074803, 2021).
melanoma (1 paper, 2017). A malignant, usually aggressive tumor composed of atypical, neoplastic melanocytes. "We can see from QPCR results that RhoBTB3 also plays an important role in 3 types of melanoma cells, especially in MV3." (PMID 28404912, 2017). "The transcription level of RhoBTB3 was significantly higher in melanoma cells than that in MC." (PMID 28404912, 2017).
meningioma (1 paper, 2018). A generally slow growing tumor attached to the dura mater. "RUNDC3B, SCG2, SLC1A3, EXT1 (as well as RHOBTB3, TSPAN7, CAV2, MLPH) were part of the NF2/SMARCB1 expression subclass of a recent study on genomic profiling of meningioma." (PMID 29662628, 2018).
osteoarthritis (1 paper, 2025). A noninflammatory degenerative joint disease occurring chiefly in older persons, characterized by degeneration of the articular cartilage, hypertrophy of bone at the margins and changes in the synovial membrane. "Its high expression in OA samples was also found in this study, so we hypothesized that RHOBTB3 is also involved in inflammation in osteoarthritis." (PMID 40909283, 2025).
uveitis (1 paper, 2023). An inflammatory process affecting a part of or the entire uvea. "Targeted genes of miR-146a were thus up-regulated and enriched in previews mentioned underline pathogenesis of uveitis such as interferon α/β, interferon γ, Rho GTPases, Miro GTPases, and RHOBTB3, metalloprotease class of deubiquitinases, RUNX1." (PMID 36969183, 2023).
cancer (8 papers, 2016 to 2025). A tumor composed of atypical neoplastic, often pleomorphic cells that invade other tissues. "The deficiency of RhoBTB3 could result in accumulation of cellular substrates which is important for cell degradation, causing an instability of cellular homeostasis, thus ultimately leading to cancers." (PMID 34093823, 2021). "This analysis revealed that TUBA1B is involved in cell cycle pathways, including “Cell Cycle,” “Signaling by Rho GTPases, Miro GTPases, and RHOBTB3,” and “Vesicle-mediated transport,” all found across nine cancer types." (PMID 39968182, 2025). "Expression of RHOBTB3 has been found moderately but significantly decreased in breast, kidney, uterus, lung, and ovary tumor samples in a cancer profiling array and in various subtypes of renal cell carcinomas." (PMID 27314390, 2016). "The authors proposed that RhoBTB3 inhibits tumorigenesis by maintaining low HIFα levels and consequently suppressing the Warburg effect, a shift towards high rate of glycolysis and lactic acid fermentation that characterizes most cancer cells." (PMID 27314390, 2016). "Their host genes had been described in individual studies with regard to their roles in either PCa progression (e.g., CRIM1, NEAT1, and STIL) or other cancers (e.g., LPP and RHOBTB3)." (PMID 33105568, 2020). "To identify circRNAs with a putative function in ccRCC initiation/progression, we selected circRNAs from host genes with putative roles in angiogenesis and hypoxia in ccRCC and other cancers including EGLN3, NOX4, and RHOBTB3." (PMID 31575051, 2019). "Although there was a high level of hsa_circ_0007444, the level of its host gene RHOBTB3 was not increased in these three types of cancer-derived exosomes." (PMID 35148775, 2022). "In The Cancer Genome Atlas (TCGA) database, the host gene RHOBTB3 was also not significantly increased in these three types of cancer tissues compared to normal tissues, and its expression did not correlate significantly with prognosis." (PMID 35148775, 2022). "In the metastasis group, the top shared upregulated genes were cancer-related with diverse functions, including tumor suppressors (SAMD9 and SEMA3B) and genes involved in growth, survival, cytoskeletal dynamics, motility, invasion, and metastasis (RHOBTB3, CYP24A1 and PTGS2)." (PMID 40605119, 2025).
tumor (8 papers, 2016 to 2025). "Evidence that RhoBTB3 functions as a tumor suppressor has been provided in xenograft experiments with Ras-transformed embryonic fibroblasts isolated from Rhobtb3 deficient mice or HeLa cells in which RHOBTB3 was silenced." (PMID 27314390, 2016). "Along with RHOBTB3 transcription, circRHOBTB3 was inevitably produced in tumor cells, but circRHOBTB3 displayed a strong antitumor effect." (PMID 35148775, 2022). "As a Rho GTPase-family ATPase, the host gene RHOBTB3 is involved in membrane transport and proteasomal degradation and can inhibit tumor growth by promoting the proteasomal degradation of HIF-α in renal cancer." (PMID 35148775, 2022). "Another interesting phenomenon was observed: the host gene RHOBTB3 presented a high transcriptional level to produce adequate RHOBTB3, which might be of great importance for the physiological function of both tumor and normal cells." (PMID 35148775, 2022). "Then we verified the differential expression of RhoBTB3 on AML bone marrow and nonleukemia/non-tumor bone marrow by RT-qPCR." (PMID 34093823, 2021).
infection (1 paper, 2025). The state of being infected such as from the introduction of a foreign agent such as serum, vaccine, antigenic substance or organism. "Re-analysis showed that there was a significant downregulation of signaling especially by Rho GTPases, Miro GTPases and RHOBTB3, suggesting that suppression of intracellular and cell-to-cell signaling was crucial to entry and establishment of Ct infection in ECS cells." (PMID 40599652, 2025).
psychiatric disorder (1 paper, 2021). A disorder characterized by behavioral and/or psychological abnormalities, often accompanied by physical symptoms. "Collectively, these data suggest that although the novel coronavirus SARS-CoV-2 is closely related to the three psychiatric disorders in terms of transcriptomic profiles, the RHOBTB3 gene is the only gene shared by all of these four diseases." (PMID 33723208, 2021).
RHOBTB3 also shares sentences with these, for which no sentence is quoted: acute myeloid leukemia (2 papers); bipolar disorder (1); bladder cancer (1); COVID-19 (1); lung carcinoma (1); prostate carcinoma (1); psychotic disorder (1); renal cell carcinoma (1); schizophrenia (1); systemic lupus erythematosus (1); uveal melanoma (1).